OR5K4 (olfactory receptor family 5 subfamily K member 4)
Description:
Odorant receptor.
Tractability: Antibody: UniProt places it where antibodies can reach, with medium confidence; UniProt predicts a signal peptide or a membrane-spanning region; its Gene Ontology location is reachable by antibodies, with medium confidence.
Gene: Protein-coding gene on chromosome 3 (98,353,854 to 98,354,819, forward strand). Ensembl gene ENSG00000196098.
Subcellular location: Cell membrane
Pathways (Reactome):
Sensory Perception: Expression and translocation of olfactory receptors
Gene Ontology:
Molecular function: odorant binding; olfactory receptor activity; G protein-coupled receptor activity
Biological process: sensory perception of smell; detection of chemical stimulus involved in sensory perception of smell; G protein-coupled receptor signaling pathway
Cellular component: plasma membrane; membrane
Genetic constraint (gnomAD): Loss-of-function variants: 14 observed, 10.69 expected, observed/expected ratio (o/e) 1.31, 90% interval 0.86 to 1.86. The upper end of that interval is the gene's LOEUF score, 1.86, which puts it in group 6 of 6, group 1 being the genes least tolerant of losing a copy. Missense variants: 391 observed, 360.98 expected, observed/expected ratio (o/e) 1.08, 90% interval 1 to 1.18. Synonymous variants: 137 observed, 128.81 expected, observed/expected ratio (o/e) 1.06, 90% interval 0.93 to 1.23.
Homologues: Orthologues: rabbit OR5K4 (84% identical), pig OR5K4 (81% identical), rat Or5k16 (77% identical), mouse Or5k17 (77% identical), rat Or5k17 (77% identical), mouse Or5k16 (76% identical), rat Or5k15 (76% identical), mouse Or5k15 (75% identical). Paralogues in human: OR5K3 (74% identical), OR5K1 (72% identical), OR5K2 (69% identical), OR5H2 (53% identical), OR5AC2 (50% identical), OR5H14 (50% identical), OR5H15 (50% identical), OR5H1 (49% identical), OR5H6 (49% identical), OR5B12 (47% identical), OR5AP2 (45% identical), OR5AS1 (45% identical), and 84 more.